ITIH4 (inter-alpha-trypsin inhibitor heavy chain 4)
Diseases named in the same sentence as ITIH4 in open-access papers (continued):
Sharing a sentence is not in itself a finding about the gene and the disease.
liver disease (5 papers, 2009 to 2022). "Notably, the effective C alleles of rs2239548 and ITIH4 are highly protective against portal hypertension." (PMID 35493725, 2022). "ITIH4 is a type II acute-phase protein involved in inflammatory responses to trauma, and its expression is altered in liver disease." (PMID 35493725, 2022).
atherosclerosis (4 papers, 2011 to 2024). A disease characterized by the build-up of fatty material and calcium deposition in the arterial wall resulting in partial or complete occlusion of the arterial lumen. "In addition to our findings on known genes associated with SMC function and atherosclerosis, we also uncovered a set of novel genes, including Itih4." (PMID 38289873, 2024). "We generated a SMC-specific TRAP mouse line to study atherosclerosis and identified Itih4 as a novel SMC-expressed gene in atherosclerotic plaques, warranting further investigation of its putative function in extracellular matrix stability and genetic evidence of causality." (PMID 38289873, 2024). "Moreover, we identified several novel genes not previously linked to SMCs in atherosclerosis, such as Anxa4, Cd276, inter-alpha-trypsin inhibitor-4 (Itih4), Myof, Pcdh11x, Rab31, Serpinb6b, Slc35e4, Slc8a3, and Spink5." (PMID 38289873, 2024). "The gene list included well-known atherosclerosis-associated genes Serpina3,42Cemip,43Thbs1,44Lum,45 and Spp146,47 but also novel genes without previous association to SMC function in atherosclerosis, such as Anxa4, Cd276, Itih4, Myof, Pcdh11x, Rab31, Serpinb6b, Slc35e4, Slc8a3, and Spink5." (PMID 38289873, 2024).
cervical cancer (4 papers, 2013 to 2025). A primary or metastatic malignant neoplasm involving the cervix. "Our previous accumulated studies have demonstrated the overexpression of a 35 kDa ITIH4 fragment selectively in cancers associated with elevated oestrogen levels, including cancers of the breast, endometrium, ovary and prostate but not in nasopharyngeal carcinoma, osteosarcoma and cervical cancer." (PMID 24252421, 2013).
rheumatoid arthritis (4 papers, 2018 to 2024). A chronic, systemic autoimmune disorder characterized by inflammation in the synovial membranes and articular surfaces. "Elevated levels of Inter-alpha-trypsin-inhibitor heavy chain 4 (ITIH4) have grabbed attention in rheumatoid arthritis (RA) pathogenesis, though its precise mechanisms remain unexplored." (PMID 39311312, 2024). "Further, the in vitro experimentation in rheumatoid arthritis fibroblast-like synoviocytes (RA-FLS) was employed to validate the in silico predictions to understand the mechanistic pathway of ITIH4 through knockdown assay after silencing ITIH4." (PMID 39311312, 2024). "Overall, the in silico enrichment analysis showed that ITIH4 might be related to chemokine-related signaling involved in rheumatoid arthritis pathogenesis." (PMID 39311312, 2024). "ITIH4 is a liver serine protease inhibitor that is highly expressed during liver development, and is an anti-inflammatory protein proposed to serve as a potential biomarker for acute ischemic stroke and rheumatoid arthritis." (PMID 34501327, 2021). "Inter‐alpha‐trypsin inhibitor heavy chain 4 (ITIH4) regulates immunity and inflammation, but its clinical role in rheumatoid arthritis (RA) patients remains unclear." (PMID 35064701, 2022).
Sepsis (4 papers, 2020 to 2025). Sepsis is defined as life-threatening organ dysfunction caused by a dysregulated host response to infection. "Abnormal levels of ITIH4 have also been observed in chronic obstructive pulmonary disease (COPD) and sepsis, correlating with disease severity." (PMID 40410722, 2025). "The decrease in ITIH1, ITIH2 and ITIH4, as compared to the increase in ITIH3, suggest a complex alteration in the protein balance of the IαI-family in sepsis." (PMID 40885913, 2025). "The decreased plasma levels of ITIH1, ITIH2 and ITIH4, as compared to the increased levels of ITIH3, suggest a complex alteration in the protein balance of the IαI-family in the pathophysiology of sepsis." (PMID 40885913, 2025).
bladder cancers (3 papers, 2014 to 2024). "In previous studies, it has been indicated that ITIH4 was significantly up-regulated in serum samples of patients with ovarian, breast or bladder cancers." (PMID 36304541, 2022). "We found that TNFRSF12A, IL1R1, ELN and CYP26B1 were overexpressed in bladder cancer cell lines, while NR1H3 and ITIH4 were downregulated." (PMID 38216619, 2024).
colon cancer (3 papers, 2008 to 2019). "In a rat model, ITIH4 was upregulated in early intestinal tumors, indicative of a role in extracellular matrix remodeling in colon tumor tissue." (PMID 31481982, 2019).
colorectal cancer (3 papers, 2019 to 2024). A primary or metastatic malignant neoplasm that affects the colon or rectum. "Expressions of ITIH3 and ITIH4 proteins in colorectal cancer and adjacent normal tissues were additionally examined via immunohistochemical (IHC) analysis." (PMID 31481982, 2019). "Expression of ITIH3 or ITIH4 in colorectal cancer and adjacent normal colorectal tissues was analyzed via IHC staining." (PMID 31481982, 2019). "Conversely, ITIH4 was upregulated in colorectal carcinoma specimens relative to adjacent normal colorectal tissues (p < 0.001)." (PMID 31481982, 2019). "Consistently, IHC score assessment showed a dramatic reduction in ITIH3 expression and, conversely, upregulation of ITIH4 in colorectal carcinoma specimens relative to adjacent normal colorectal tissues (p < 0.001 in both cases)." (PMID 31481982, 2019). "In this study, we explored that the relative expression of the Col1a2, ITIH4, MMP7, and MSX2 are increased in the mice who induced colorectal cancer (the COL group) compared with the Normal group." (PMID 38637796, 2024). "The gene profiles (Col1a2, ITIH4, MMP7, and MSX2) were identified as critical markers in colorectal cancer." (PMID 38637796, 2024). "Growing evidence has indicated that the genes of Col1a2, ITIH4, MMP7, and MSX2 profiles could be critical markers for identifying colorectal cancer." (PMID 38637796, 2024).
endometrial cancer (3 papers, 2021 to 2024). Primary or metastatic malignant neoplasm involving the endometrium (mucous membrane that lines the endometrial cavity). "Six of them were upregulated in endometrial cancer patients (CLU, SERPINC1, ITIH4, C1RL, APOC3 and DSC1), while ten were downregulated (APCS, C9, APOA1, ALB, APOA4, CFHR1, ITIH2, and ACTB)." (PMID 39194522, 2024). "The observation of enhanced levels of clusterin, ITIH4, antithrombin-III, and C1RL in sera of endometrial cancer patients allowed a mathematical model to be built to detect cancer samples." (PMID 36232415, 2022). "Quantification of protein expression revealed the upregulation of CLU, ITIH4, SERPINC1, and C1RL in endometrial cancer samples compared to the sera of control subjects." (PMID 34298850, 2021). "Several blood-based protein biomarker candidates for endometrial cancer detection were suggested, including the Apolipoprotein family (APOA1/4, APOC1/2/3, and APOE), Clusterin (CLU), Inter-alpha-trypsin inhibitor heavy chain (ITIH2 and ITIH4), and Antithrombin III (ATR/SERPINC1)." (PMID 39194522, 2024).
glaucoma (3 papers, 2018 to 2024). Increased pressure in the eyeball due to obstruction of the outflow of aqueous humor. "Besides, TTR and ITIH4 have been previously identified altered in the human aqueous humor of glaucoma patients." (PMID 32585848, 2020). "The proteins ITIH4 and CFH were found in higher concentrations in 10 and 14 month old glaucomatous mice (DBA/2J_G10 and DBA/2J_G14) compared to preglaucomatous stage (DBA/2J_G4), therefore suggesting changes in the transition phase to glaucoma." (PMID 32585848, 2020).
liver cancer (3 papers, 2014 to 2022). An epithelial or non-epithelial malignant neoplasm that arises from the liver. "Although Itih4 has not been implicated in PDA development, it has been shown to be involved in maintaining viability downstream of the critical PDA mediator c-myc in a model of liver cancer." (PMID 24788257, 2014).
pancreatic cancer (3 papers, 2015 to 2022). "However, several other known acute-phase reactants were found not to be elevated (e.g., AHSG, SERPINA3, ITIH4, FN, F2, F8, SAP, and CD163), arguing that there may be some specificity in the inflammatory response to pancreatic cancer." (PMID 29232830, 2017).
amyotrophic lateral sclerosis (2 papers, 2014). Amyotrophic lateral sclerosis (ALS) is a neurodegenerative disease characterized by progressive muscular paralysis reflecting degeneration of motor neurons in the primary motor cortex, corticospinal tracts, brainstem and spinal cord. "ITIH4 protein is a 120KD glycoprotein, which is prone to be cleaved to produce fragments of different length, such as 100 kDa and 35 kDa fragment, which have been identified as the biomarkers for Down syndrome, amyotrophic lateral sclerosis, and cancer." (PMID 25273983, 2014).
autoimmune disease (2 papers, 2019 to 2022). A disorder resulting from loss of function or tissue destruction of an organ or multiple organs, arising from humoral or cellular immune responses of the individual to their own tissue constituents. "TTR, ITIH4, C3, and CRP have been previously reported in the disease pathogenicity and inflammation of autoimmune diseases, affecting synovial joints with restricted joint movements, whereas HP has been linked with irregularity in the homeostasis of free hemoglobin in OA." (PMID 36569927, 2022).
Cirrhosis (2 papers, 2019 to 2021). A chronic disorder of the liver in which liver tissue becomes scarred and is partially replaced by regenerative nodules and fibrotic tissue resulting in loss of liver function. "We observe lower intensities in the non-fucosylated glycopeptides of proteins (hemopexin, clusterin, ITIH4, fibrinogen) reported to decrease in cirrhosis while the non-fucosylated glycopeptide of alpha-2 macroglobulin has higher intensity in cirrhosis in line with its increased serum concentration." (PMID 34857845, 2021).
diabetes (2 papers, 2017 to 2021). "Our results showed that four isoforms of ITIH4 and one isoform of SERPINA1 (spots 669 and 683) had lower abundance in the diabetes remission group than in the non-diabetic group and an intermediate value in the persistent diabetes group." (PMID 34501327, 2021). "Regarding differences among the non-diabetic, diabetes remission, and persistent diabetes groups, considering the samples obtained before and after surgery as a whole, we found different abundances in nine spots from five proteins: CP, SERPINA1, ITIH4, plasminogen (PLG), and FGG." (PMID 34501327, 2021).
lung adenocarcinoma (2 papers, 2021). A carcinoma that arises from the lung and is characterized by the presence of malignant glandular epithelial cells. "In order to verify the clinical value of the model, we finally examined the expression of FERMT2, FKBP3, SMAD9, GATA2 and ITIH4 in 30 lung adenocarcinoma tissues by immunohistochemistry, considering the availability of antibodies." (PMID 33648465, 2021).
schwannoma (2 papers, 2019 to 2024). A benign, usually encapsulated slow growing tumor composed of Schwann cells. "ITIH4, a secreted protein that was enriched in conditioned media from schwannoma cells surviving radiotherapy, displayed closed chromatin and RNA suppression following snARC-seq suppression of KDM5C with radiotherapy." (PMID 38216587, 2024).
allergic asthma (1 paper, 2025). A asthma with a basis in a pathological type I hypersensitivity reaction. "This aligns with the observed downregulation of granzyme A signaling, suggesting that ITIH4 may attenuate cytotoxic immune responses in allergic asthma." (PMID 40410722, 2025).
Arthritis (1 paper, 2018). Inflammation of a joint. "The expression of ITIH4 was increased in inflamed synovium at day 14 in pGIA, suggesting the association with arthritis." (PMID 29636082, 2018).
asthma (1 paper, 2025). "We identified the key biological processes influenced by ITIH4 in the OVA-induced asthma mice, by activating granzyme A signaling, iron uptake and transport, and the ESCRT." (PMID 40410722, 2025). "Furthermore, ITIH4 regulated gut immune response, metabolic regulation, and protein processing in OVA-induced asthma models." (PMID 40410722, 2025). "Furthermore, ITIH4 also suppressed IL-5 and IL-13 levels in the intestinal tissues of OVA-induced asthma mice (p < 0.05), suggesting a systemic immunomodulatory effect that extends beyond the lungs." (PMID 40410722, 2025).
babesiosis (1 paper, 2023). Babesiosis refers to a condition caused by microscopic parasites that infect the red blood cells. "Other identified proteins that differentiated uncomplicated from complicated babesiosis were various complement cascade components (CFI, CFP, C2, SERPING1, C8G), extracellular matrix components (TGFBI), acute phase proteins (ORM1, ITIH2, ITIH4, FGA, TF, RBP4) and lipoproteins (apoE)." (PMID 37353646, 2023).
colitis (1 paper, 2017). Inflammation of the colon. "After induction of acute colitis with DSS, we found with EdgeR and CuffDiff2 analyses that the expression of 11 genes (Clps, Ddx60, Fgb, Fgg, Ifi44, Ifit2, Isg15, Itih3, Itih4, Oas3 and Usp18), which are involved in antimicrobial response, was increased in MMP-9−/− compared to WT mice." (PMID 28561062, 2017).
colorectal adenoma (1 paper, 2024). An adenoma that arises from the colon or rectum. "A recent study found that serum biomarkers F5, ITIH4, LRG1, and VTN were elevated in colorectal adenoma patients as well as in a mouse model of colorectal adenomas." (PMID 38383428, 2024).
congenital cataracts (1 paper, 2022). "Group 5 (congenital cataracts) also shows abundant proteins involved in protein metabolism, among which three proteins—corticosteroid-binding globulin-SERPINA6, apolipoprotein A-IV (APOA4), and inter-alpha-trypsin inhibitor heavy chain H4 (ITIH4)—were downregulated compared to other groups." (PMID 36362243, 2022).
coronary atherosclerosis (1 paper, 2024). Atherosclerosis of the coronary vasculature. "Interestingly, PLG, ITIH4, FN1, and ANGPTL4, all protective against MI, were also inferred to be protective against coronary atherosclerosis." (PMID 40027362, 2024).
endometriosis (1 paper, 2020). The growth of functional endometrial tissue in anatomic sites outside the uterine body. "Five proteins were found exclusively in the endometriosis groups: PRDX1, H2A type 2-C, ANXA2, ITIH4, and the tubulin α-chain." (PMID 32106990, 2020).
epilepsy (1 paper, 2024). A brain disorder characterized by episodes of abnormally increased neuronal discharge resulting in transient episodes of sensory or motor neurological dysfunction, or psychic dysfunction. "Surprisingly, we also identified many differential proteins such as UGGT2, SEMG1, PDIA4, ROR1, NIF3L1, and ITIH4, that have not previously been directly reported with epilepsy." (PMID 38585359, 2024).
gestational diabetes (1 paper, 2025). Carbohydrate intolerance first diagnosed during pregnancy. "Similarly, in studies of gestational diabetes mellitus (GDM), proteomic techniques such as mass spectrometry have revealed several potential urinary biomarkers such as coagulation factor IX and the trans-α-trypsin inhibitor heavy chain H4 (ITIH4)." (PMID 40149657, 2025).
hereditary angioedema (1 paper, 2026). Hereditary angioedema (HAE) is a genetic disease characterized by the occurrence of transitory and recurrent subcutaneous and/or submucosal edemas resulting in swelling and/or abdominal pain. "The resulting alterations in ITIH4 isoforms or cleavage patterns have been observed in various pathologies, making it an intriguing candidate biomarker for inflammatory diseases such as hereditary angioedema (HAE)." (PMID 41484981, 2026).
hydatidiform mole (1 paper, 2013). A gestational trophoblastic disorder characterized by marked enlargement of the chorionic villi, hyperplasia of the villous trophoblastic cells and hydropic changes. "Our results demonstrated that the 35 kDa fragment of ITIH4 was overexpressed in healthy pregnant women and patients with hydatidiform mole, relative to the controls." (PMID 24252421, 2013). "The data of the present study, when taken together with those of our previous reports, suggest that overexpression of the 35 kDa fragment of ITIH4 is oestrogen-related and occurs in patients with selective cancers, hydatidiform mole as well as healthy women who are pregnant." (PMID 24252421, 2013). "When the 35 kDa serum ITIH4 fragment cluster was analysed by densitometry, significant up-regulated expression was detected in the women who were pregnant (+8.7-fold; p = 0.0002) as well as in the patients with hydatidiform mole (+5.6-fold; p < 0.0001) relative to the controls." (PMID 24252421, 2013). "Overexpression of the 35 kDa fragment of ITIH4 was not restrictive to patients with cancers but also occurred in women who were pregnant and those diagnosed with hydatidiform mole." (PMID 24252421, 2013).
Hypercholesterolemia (1 paper, 2017). An increased concentration of cholesterol in the blood. "Besides its role as APR, ITIH4 is associated with hypercholesterolemia and may play an important role in liver regeneration." (PMID 29049355, 2017).
medulloblastoma (1 paper, 2024). A malignant, invasive embryonal neoplasm arising from the cerebellum. "However, two proteins, ALDOC and ITIH4, were significantly elevated in medulloblastoma patients within the Reichl cohort." (PMID 38350915, 2024).
migraine (1 paper, 2024). "Additionally, ITIH4 (OR = 0.862, p = 4.69 × 10−5) and ADGRF5 (OR = 0.964, p = 8.74 × 10−5) were significantly associated with a decreased risk of any migraine." (PMID 38898596, 2024). "While ITIH4 was also associated with migraine risk, co‐localization analysis revealed that the causal variant (rs3755799) associated with both ITIH4 and any migraine is the same as the one linked to ITIH1 and any migraine." (PMID 38898596, 2024).
myelodysplastic syndrome (1 paper, 2012). A clonal hematopoietic disorder characterized by dysplasia and ineffective hematopoiesis in one or more of the hematopoietic cell lines. "Nevertheless, in light of the observations from RAEB-1, RCMD, and previous literature it seems that ITIH4 alterations could be a marker specific for myelodysplastic syndrome." (PMID 22568928, 2012).
osteoarthritis (1 paper, 2021). A noninflammatory degenerative joint disease occurring chiefly in older persons, characterized by degeneration of the articular cartilage, hypertrophy of bone at the margins and changes in the synovial membrane. "Indeed, citrullinated proteins, including ITIH4, were mainly located in RA joints (not osteoarthritis joints), and from our mouse analysis, this was mainly driven by synovium proliferation with neutrophil infiltration." (PMID 34299252, 2021).
preeclampsia (1 paper, 2022). Preeclampsia is a hypertensive disorder of pregnancy that is characterized by new-onset hypertension with proteinuria presenting after 20 weeks of gestation, and depending on mild or severe forms may initially present with severe headache, visual disturbances, and hyperreflexia. "However, we discovered two novel ITIH protein biomarkers of preeclampsia, which have not been reported previously; ITIH3 and ITIH4 were both increased in EOPE and LOPE whereas ITIH2 was the only one increased in LOPE." (PMID 36351970, 2022).
renal carcinoma (1 paper, 2021). A carcinoma arising from the epithelium of the renal parenchyma or the renal pelvis. "The results showed that EIF4EBP1, FOXM1, PLG, and VWF were highly expressed in renal carcinoma compared with normal renal tissue, and ADAM8, CGN, G6PC, ITIH4, and MMP3 were low in expression in renal carcinoma compared with normal renal tissue." (PMID 33968297, 2021).